TSC1 (TSC complex subunit 1)
Diseases named in the same sentence as TSC1 in open-access papers (continued):
Sharing a sentence is not in itself a finding about the gene and the disease.
colitis (5 papers, 2018 to 2025). Inflammation of the colon. "Altogether, the increased mTOR activity caused by TSC1 deficiency in macrophages might contribute to the accelerated DSS-induced colitis in TSC1cKO mice and high expression of IL-17A, IL-17F, and IFN-γ in macrophages." (PMID 36465179, 2022). "Herein, we studied the cytokine expression profile of wild-type (WT) and TSC1-deleted macrophages after LPS stimulation in vitro and the pathogenesis of dextran sodium sulfate (DSS)-induced colitis in mice with myeloid-specific TSC1 deletion (TSC1cKO mice)." (PMID 36465179, 2022). "Mice with a myeloid-specific deletion of TSC1 gene (TSC1cKO) displayed severe dextran sodium sulfate (DSS)-induced colitis accompanied by high levels of IL-17A, IL-17F, and IFN-γ." (PMID 36465179, 2022). "Defect of IGF2BP2 promoted M1 response, leading to enhancing DSS induced experimental colitis development, but impaired M2 activation through stabilizing TSC1 and PPARγ mRNA." (PMID 34258163, 2021). "However, the underlying molecular mechanism and cellular components involved in TSC1-mTOR-dependent regulation of colitis remain largely elusive." (PMID 36465179, 2022). "In conclusion, we herein demonstrated that TSC1-mTOR signaling pathway negatively regulated Th1/Th17-type cytokine expression in LPS-stimulated macrophages and exacerbated pathogenesis of colitis in mice via reprogramming metabolism and STAT3-RORγT/T-bet pathway." (PMID 36465179, 2022). "In addition, overactivation of mTOR signaling through deletion of TSC1, an upstream negative regulator of mTOR, leads to reduced Treg suppressive activity in a mouse model of colitis." (PMID 29599783, 2018). "Importantly, mTOR deletion can reverse the more severe symptoms of acute colitis in TSC1cKO mice, as shown by significantly extended survival time, decreased macroscopic scores, and longer colon length in TSC1/mTORcKO mice compared with TSC1cKO mice." (PMID 36465179, 2022). "However, TSC1 deficiency inhibits IFN-γ expression in CD8+ T cells after bacterial antigen-stimulation and enhances IFN-γ production by CD4+ T cells and Th1 differentiation in mice with induced colitis." (PMID 36186130, 2022).
developmental delay (5 papers, 2020 to 2022). "One patient (ID 43) with a TSC1 duplication with seizure onset at 25 months also had mild global developmental delay, microcephaly, and hypopigmented macules." (PMID 34469436, 2021).
Dravet syndrome (5 papers, 2018 to 2025). "A gene-based collapsing analysis highlighted an increased variant burden in CHD2, FLNA and TSC1 (P < 0.05) in Dravet syndrome compared with GEL SCN1A controls that was not significant after correction for multiple comparisons." (PMID 37006128, 2023). "Preferred adjunctive applications of the KD include genetic epilepsies, such as SCN1A-related Dravet syndrome, TSC1/TSC2-related tuberous sclerosis complex, and UBE3A-related Angelman syndrome." (PMID 40290041, 2025).
focal epilepsy (5 papers, 2019 to 2025). A seizure caused by a localized disorder. "Four TSC1 variants were identified in four unrelated families with DEE or focal epilepsy." (PMID 40217423, 2024). "Additionally, we identified two heterozygous TSC1 variants that affected four individuals with focal epilepsy from two unrelated families." (PMID 40217423, 2024). "Two patients with germline mutation (one each with TSC1 and DEPDEC5) who were operated due to drug-resistant focal epilepsy continued to have frequent seizures, post-surgery." (PMID 38074073, 2023). "The mTOR genes including DEPDC5, TSC1 and TSC2 have been associated with focal epilepsy, as was the case in our study in which the mTOR genes had the highest yield (13/32), although the yield was relatively low in some previous studies." (PMID 31875159, 2019). "Two TSC1 de novo variants were identified in two patients with developmental and epileptic encephalopathy (DEE), and two co-segregating variants were identified in four patients with focal epilepsy." (PMID 40217423, 2024). "Recent studies have linked mutations in several genes involved in the mTOR signaling pathway - such as TSC1, TSC2, MTOR, DEPDC5, NPRL2, and NPRL3 - to the development of focal epilepsies in affected individuals." (PMID 40546503, 2025).
Pancreatic NETs (5 papers, 2014 to 2025). "Mutation and loss of function of TSC1 and/or TSC2 have also been shown to occur consistently in a variety of sporadic cancers including bladder, kidney, pancreatic neuroendocrine tumors, and PEComa." (PMID 33891611, 2021). "Additionally, although low expression of PTEN, TSC1, and TSC2 have been found in pancreatic NETs, TSC1 and TSC2 expression appear preserved in small intestinal NET [29•]." (PMID 25092520, 2014). "Pancreatic NETs frequently exhibit changes in genes such as MEN1, DAXX, ATRX, TSC1, TSC2, CDKN1A, and CDKN1B, along with alterations in CDKN2A and SETD2 in metastatic lesions." (PMID 41426335, 2025). "Pancreatic NETs (PanNETs) have been among the most studied, and research so far has outlined a series of recurring features, as inactivation of MEN1, VHL, TSC1/2 genes and hyperactivation of the PI3K/mTOR pathway." (PMID 29321190, 2018).
steatosis (5 papers, 2011 to 2025). Increased lipid within the cytoplasm of cells. "The most pervasive explanation for the ‘steatosis-protective’ phenotype in the Tsc1-null livers is the mTORC1 feedback inhibition of Akt." (PMID 25646773, 2015). "A recent study showed that the Tsc1-/- livers are protected from steatosis through ‘stress’-induced responses, including hepatic synthesis of FGF21, but we were unable to find significant differences in FGF21 expression in livers of various genotypes." (PMID 25646773, 2015). "Previously, we showed that acute over-expression of Myr-Akt induced steatosis in the Tsc1-/- hepatocytes." (PMID 25646773, 2015). "Further, Akt activity was suppressed in the Tsc1-null livers, and acute Akt activation (via Myr-Akt expressing adenovirus) induced steatosis in the Tsc1fl/fl;AlbCre mice." (PMID 25646773, 2015). "We have previously shown that the steatosis-resistant phenotype in the Tsc1-/- liver was completely reversed by rapamycin treatment suggesting that mTORC1 activity prevents diet-induced steatosis." (PMID 25646773, 2015). "Instead, mice with hepatocyte-specific deletion of Tsc1 were resistant to high-fat diet induced steatosis." (PMID 25646773, 2015). "In this study, we used genetic models to examine the role of S6K1 and Akt in protecting Tsc1-/- livers against steatosis." (PMID 25646773, 2015). "When Akt dominates over mTORC1 (e.g., Pten−/−), steatosis ensues, whereas when mTORC1 overshadows Akt (e.g., Tsc1−/−), fat deposition is suppressed." (PMID 21479224, 2011). "Unexpectedly, the Tsc1-null livers showed minimal signs of steatosis even under high-fat diet condition." (PMID 21479224, 2011). "To determine if the resistance to steatosis in the Tsc1−/− mice stems from mTORC1 hyperactivity, we treated a cohort of mice on HFD with rapamycin." (PMID 21479224, 2011). "We found that the deletion of S6k1 in the Tsc1-null livers restored steatosis under HFD conditions." (PMID 25646773, 2015). "However, constitutive activation of mTORC1 following Tsc1 deletion surprisingly protects against diet-induced steatosis." (PMID 25646773, 2015). "In support of this, the Tsc1−/− livers were resistant to high-fat diet-induced steatosis, and treatment with rapamycin abolished this ‘protection’ resulting in hepatic TG accumulation that was equivalent to that seen in the wild-type hepatocytes under high-fat diet condition." (PMID 21479224, 2011). "While the Pten-null livers developed profound steatosis, the Tsc1-null livers had low TG stores." (PMID 21479224, 2011). "This phenotypic difference correlated closely with their relative Akt and mTORC1 activities and suggested that the Tsc1−/− hepatocytes could be protected from steatosis due to the feedback suppression of Akt by mTORC1." (PMID 21479224, 2011). "On histologic analysis, the livers from the wild-type and mutant mice in the NCD group were indistinguishable, but under HFD condition, the Tsc1+/+ mice developed significant steatosis while the Tsc1−/− livers showed minimal change based on H&E and Oil Red “O” staining." (PMID 21479224, 2011). "The correlation between hepatic Akt activity and steatosis led us to predict that mTORC1-mediated suppression of Akt may protect the Tsc1−/− liver from TG accumulation." (PMID 21479224, 2011). "Moreover, steatosis can be induced in the Tsc1−/− hepatocytes with the expression of Myr-Akt." (PMID 21479224, 2011). "Inhibition of TORC1 through overexpressing TSC1,2, or overexpressing Proline-rich Akt substrate 40 kDa (PRAS40), or by feeding flies with rapamycin, all induced steatosis in oenocytes, as observed following Hnf4 knockdown in oenocytes." (PMID 40236168, 2025). "This was confirmed by H&E histology and Oil Red ‘O’ staining highlighting the lack of macrovesicular steatosis in the Tsc1-/-;Pten-/- livers." (PMID 25646773, 2015).
steatosis (continued). "Together, these findings indicate that persistent Akt activation in the Tsc1-/- livers did not result in steatosis, and conversely, up-regulation of mTORC1 in the Pten-/- livers protected against Akt-induced steatosis." (PMID 25646773, 2015). "These biochemical results are confirmed by histologic analyses showing large lipid droplets in livers of all genotypes except for the Tsc1-/- livers under HFD condition (HFD)., These findings indicate that S6k1 suppresses steatosis in the setting of constitutive mTORC1 activation." (PMID 25646773, 2015). "Although mTORC1 has been implicated in de novo lipogenesis in cells, the lack of TG accumulation in the Tsc1-null livers when challenged with HFD suggests that mTORC1 is not the primary ‘driver’ of steatosis in vivo." (PMID 21479224, 2011). "To directly address the hypothesis that the lack of steatosis in the Tsc1-/- liver is a result of Akt suppression, we deleted the dual-specific phosphatase, Pten, in hepatocytes of the Tsc1fl/fl;AlbCre mice to force Akt activation and overcome mTORC1-induced inhibition of PI3K/Akt." (PMID 25646773, 2015).
Angiofibroma (4 papers, 2014 to 2024). A benign neoplasm of fibrous tissue in which there are numerous small and large, frequently dilated, vascular channels. "A germline mutation of the TSC1 or TSC2 gene, leading to activation of the mammalian target of rapamycin (mTOR) pathway, accounts for the pathogenesis of TSC-associated angiofibromas." (PMID 24558502, 2014). "The authors did not observe a difference in the number of angiofibromas, which could be due to the low number of patients with a TSC1 mutation, although there appears to be a trend of increasing numbers of angiofibromas in the presence of a TSC2 gene mutation." (PMID 38658236, 2024).
breast tumors (4 papers, 2015 to 2023). "Next, analysis of an independent dataset from primary breast tumors also showed low TSC1 and TSC2 expression to be specifically associated with lung metastasis." (PMID 26167915, 2015). "Aberrant regulation of TSC1 occurs frequently in many tumorigenic processes, highlighting the possible critical role of precise regulation of TSC1 in breast tumor progression." (PMID 36539038, 2023). "Invasive breast tumors have lower protein expression of TSC1 and TSC2 compared to the normal mammary epithelium." (PMID 35608730, 2022). "The hypothesis was led by the observation that primary breast tumors with relatively low TSC1/2 expression and predicted enhancement of mTORC1 signaling preferentially metastasize to lung." (PMID 26167915, 2015). "In addition, according to the present model, Tsc1−/− mice do not develop breast tumors (the longest observation period reached 6 months), which is supposed to be related with the low level of activated AKT." (PMID 26795955, 2016).
colon cancer (4 papers, 2017 to 2025). "The results suggested that ATG101 and TSC1 levels in colon cancer tissues were significantly higher than normal tissues." (PMID 34315829, 2021). "Using nanotitanium dioxide to reduce the expression of TSC1 in colon cancer cells may become a new method for the treatment of colon cancer." (PMID 35572821, 2022). "We obtained the risk score of each case with colon cancer; risk score = (0.46121 × expression of ULK3) + (0.650715 × expression of ATG101) + (1.521474 × expression of MAP1LC3C) + (0.641122 × expression of TSC1) + (0.243022 × expression of DAPK1) + (-0.17015 × expression of SERPINA1)." (PMID 34315829, 2021). "We identified 6 prognostic-related ARGs (ULK3, ATG101, MAP1LC3C, TSC1, DAPK1 and SERPINA1) to formulate a novel autophagy-related signature, which could stably predict the survival of patients and indicate the extent of immunosuppressive microenvironment in colon cancer." (PMID 34315829, 2021).
depression (4 papers, 2015 to 2025). "ASD was observed at a significantly higher frequency in participants with TSC2 than those with TSC1 mutations, while ADHD, anxiety disorder, and depressive disorder were more associated with TSC1 rather than TSC2, indicating a more severe neuropsychiatric phenotype being associated with TSC2." (PMID 39852149, 2025). "ADHD, anxiety disorder, and depressive disorder were associated with TSC1 rather than TSC2 (ADHD TSC1 = 17.6%; TSC2 = 16%, p = 0.6881; anxiety disorder TSC1 = 10.1%; TSC2 = 8.6%; p = 0.7809; depressive disorders TSC1 = 10%; TSC2 = 5.2%; p = 0.0509)." (PMID 39852149, 2025).
fibroma (4 papers, 2024 to 2025). A non-metastasizing neoplasm arising from the fibrous tissue. "The chance of a TSC2 mutation was 10-fold higher in the presence of ungual fibromas, although these data should be viewed with caution because of the wide confidence interval associated with the small number of cases with a TSC1 mutation." (PMID 38658236, 2024). "In this patient, the main clinical manifestations were hypomelanotic macules and ungual fibromas; hence, we speculate that the variant TSC1: c.1030‐2A>T is associated with a mild phenotype of TSC." (PMID 38439608, 2024).
Focal cortical dysplasia (4 papers, 2018 to 2022). A type of malformation of cortical development that primarily affects areas of neocortex. "Focal cortical dysplasias (FCDs) are localized MCDs, formerly believed to mostly result from a toxic insult to the developing brain, but recently also associated with DEPDC5 mutations and somatic mutations in MTOR, PIK3CA, AKT3, PTEN, TSC1 and TSC2." (PMID 35323703, 2022).
leukemia (4 papers, 2019 to 2025). A malignant (clonal) hematologic disorder, involving hematopoietic stem cells and characterized by the presence of primitive or atypical myeloid or lymphoid cells in the bone marrow and the blood. "A gene set enrichment analysis (GSEA) showed that the gene expression pattern in CBAP-deficient leukemia cells was significantly correlated with signatures of TSC1/TSC2-dependent rapamycin-sensitive genes." (PMID 30266989, 2019). "PTEN or TSC1 deficiency induces mTORC1 hyperactivation that leads to HSC exhaustion and leukemia in mice." (PMID 36250465, 2022). "Although deletion of the Tsc1 gene does not directly trigger leukemia, Tsc1-knockout mice are prone to developing myeloproliferative disorder, which is a hematological disease with a high risk of progression into acute leukemia." (PMID 34067520, 2021). "However, unlike mice with inducible deletions of PTEN or TSC1, which developed rapid HSC exhaustion and/or leukemia, SZT2-KO mice survived more than 1 year without obvious abnormalities." (PMID 36250465, 2022).
liver hemangioma (4 papers, 2010 to 2025). A hemangioma arising from the liver. "In mice, homozygous disruption of Tsc1 or Tsc2 is lethal during embryogenesis, and heterozygous Tsc1+/− and Tsc2+/− mice develop renal cystadenomas, liver hemangiomas, and infrequently, paw angiosarcomas." (PMID 28695825, 2017). "Tamoxifen was used to treat Tsc1+/- mice (in 129/sv background) and was found to reduce the frequency and severity of liver hemangiomas." (PMID 20146790, 2010).
neurofibromatosis type 1 (4 papers, 2017 to 2025). A clinically heterogeneous, neurocutaneous genetic disorder characterized by cafe-au-lait spots, iris Lisch nodules, axillary and inguinal freckling, and multiple neurofibromas. "For example, the autosomal-dominant syndromes neurofibromatosis type 1 (NF1) and tuberous sclerosis (TS) are caused by inactivating mutations in NF-1 and TSC1/2, respectively." (PMID 29255447, 2017).
premature ovarian failure (4 papers, 2012 to 2022). "In ovaries, specific deletion of Tsc1 or Tsc2 in oocytes leads to primordial follicle depletion, causing premature ovarian failure." (PMID 23335988, 2013). "In the ovary, oocyte specific disruption of either Tsc1 or Tsc2 leads to global activation of primordial follicles at the time of puberty, resulting in early follicle depletion and premature ovarian failure (POF)." (PMID 23335988, 2013).